RNU6-349P (RNA, U6 small nuclear 349, pseudogene)
Gene: Small nuclear RNA gene on chromosome 18 (6,454,962 to 6,455,068, forward strand). Ensembl gene ENSG00000199272.
Homologues: Orthologues: chimpanzee U6 (94% identical), macaque U6 (87% identical), dog U6 (67% identical), mouse Gm22880 (63% identical), rabbit U6 (60% identical), rat LOC120094871 (55% identical). Paralogues in human: RNU6-16P (79% identical), RNU6-12P (78% identical), RNU6-13P (78% identical), RNU6-144P (78% identical), RNU6-32P (78% identical), RNU6-1 (77% identical), RNU6-11P (77% identical), RNU6-17P (77% identical), RNU6-18P (77% identical), RNU6-19P (77% identical), RNU6-2 (77% identical), RNU6-20P (77% identical), and 1288 more.